IL6 (interleukin 6)
Diseases named in the same sentence as IL6 in open-access papers (continued):
Sharing a sentence is not in itself a finding about the gene and the disease.
asthma (continued). "Significantly IL6 variants have been associated with asthma and childhood onset of asthma." (PMID 33281808, 2020). "IL-6 signaling has been previously suggested as a biomarker for asthma and circulating levels of IL-6 has been shown to be increased in individuals with asthma and has been associated with high dose ICS in adult onset asthma." (PMID 32381094, 2020). "The NF-κB pathways regulate T-cell differentiation via regulation the expression of pro-inflammatory genes in asthma, particularly those encoding IL-6 and TNF-α, suggesting that B. thetaiotaomicron may have a potential role in this regulation." (PMID 33339172, 2020). "Interestingly, in our asthma cohort higher concentrations of BAL IL-6 was associated with increased circulating H3cit." (PMID 32685129, 2020). "Moreover, IL-6 is considered to have a causal role in severe asthma and sustain the utility of monitoring this cytokine as biomarker in IL-6 high asthma." (PMID 30605486, 2019). "However, while high serum IL‐6 is associated with severe asthma in humans and while IL‐6 contributes to allergen‐induced AHR in mice, IL‐6 does not appear to play a role in O3‐induced AHR even though it does contribute to neutrophil recruitment." (PMID 31544355, 2019). "Overexpressed CD44 could further induce the expression of asthma-associated molecules, including IL-6, IL-8 and intercellular adhesion molecule 1 (ICAM), which promote progression of asthma." (PMID 29471827, 2018). "NO2, PM2.5, and PM10 have been reported to be the primary constituents of TRAP, and long-term exposure to these pollutants in mice has been shown to lead to elevated levels of interleukin-6, a proinflammatory cytokine associated with inflammation and pulmonary diseases such as asthma." (PMID 30631772, 2018). "IL-6 can stimulate proliferation of lymphocytes, inhibit the action of regulatory T lymphocytes (Tregs) and conversely enhance Th17/IL-17 synthesis, which is associated with neutrophilic inflammation and steroid insensitivity in asthma." (PMID 30157189, 2018). "Furthermore, IL-6-deficient mice showed a marked decrease in IgE levels, a signature asthma antibody, in both BALF and serum as compared with their WT counterparts." (PMID 30534125, 2018). "Although IL-6 was implicated in the pathogenesis of allergic asthma both in human patients and in several mouse models of asthma, the contribution of this cytokine in the most clinically relevant mouse model—administration of HDM at low doses—has not been addressed." (PMID 30534125, 2018). "Specific ablation of IL-6 in macrophages reduced key indicators of type 2 allergic inflammation, including eosinophil and Th2 cell accumulation in the lungs, production of IgE and expression of asthma-associated inflammatory mediators." (PMID 30534125, 2018). "In summary, this study demonstrated that IL-4, IL-6, and IL-12 levels might be associated with the moderate-to-severe asthma of children." (PMID 28328807, 2017). "IL-6 was associated in the asthma group with age (β = 0.19 [95% CI, 0.11–0.27]) and BMI (β = 0.25 [95% CI, 0.17–0.32]), as well as hsCRP (β = 0.6 [95% CI, 0.54–0.67]), fibrinogen (β = 0.29 [95% CI, 0.22–0.37]), TNFα (β = 0.29 [95% CI, 0.22–0.37]), and ETP (β = 0.35 [95% CI, 0.28–0.42])." (PMID 28429138, 2017). "In the lung, ORMDL3 activates the UPR via the ATF6 pathway, increasing transcription of endoplasmic reticulum–associated protein degradation pathway-specific genes (Edem-1) and regulating the expression of IL-6, which has been implicated in the pathogenesis of asthma." (PMID 27623174, 2017). "VEGF and IL-6 are among these compounds that have been linked to asthma pathology." (PMID 29230220, 2017). "Thus, further understanding of the mechanisms through which ASMCs‐derived IL‐6 is regulated would be important to uncover the pathogenic mechanisms of asthma." (PMID 28474507, 2017).
asthma (continued). "Consequently, it is believed that IL-4, IL-6, and IL-12 levels in PB were associated with lung function and cellular immune function in children with moderate-to-severe asthma." (PMID 28328807, 2017). "Diagnoses of asthma (β = 0.081, s.e. = 0.041, p = 0.048), eczema (β = 0.102, s.e. = 0.042, p = 0.014) or both (β = 0.127, s.e. = 0.055, p = 0.020) before the age of 10 years were all associated with increased serum IL-6 at the age of 9 years." (PMID 27476619, 2017). "Reductions in this key transcriptional moderator can favor the activation of NF-κB and the expression of the proinflammatory cytokines IL-6 and IL-8 in susceptible immature lung tissue, which may later lead to the development of asthma." (PMID 24996444, 2014). "This suggests that deregulation of the IL-6 methylation profile could play an important role in a pro-allergic skew of allergen-naïve DCs, and possibly is an early indication of asthma predisposition." (PMID 23950928, 2013). "Given that increased IL-6 and IL-8 in lung fluid, sputum, and blood have been associated with clinical diseases, including chronic obstructive pulmonary disease and asthma, we believe that these in vitro results are applicable to lung inflammation and other human health effects." (PMID 16507455, 2006). "IL-6 may serve as a biomarker to identify children most susceptible to radon-related airway inflammation, guiding personalized mitigation strategies and targeted interventions to improve asthma outcomes." (PMID 42188340, 2026). "Interleukin-6 (IL-6), a pleiotropic cytokine implicated in both Type 2-low airway inflammation and radon-related lung carcinogenesis, may represent a key mechanistic link between radon exposure and asthma morbidity." (PMID 42188340, 2026). "Severe asthma is often associated with Th2 low and mixed endotype, increased neutrophils and extracellular DNA (eDNA) in patient sputum, with an increase in type 1 cytokines IL‐1β and IL‐6 at the late onset of the disease, and unresponsiveness to corticosteroids or specific biologicals." (PMID 39466641, 2025). "A systematic review concluded that TNF-α and IL-6 may influence the risk of asthma." (PMID 37020645, 2023). "T2-low asthma is more prevalent in countries with higher levels of airway pollutants characterized by pathogen-associated molecular patterns (PAMPs) that activate macrophages in the airway epithelium and lead to the release of TLRs, IL-8 and IL-6 and subsequent pulmonary neutrophil recruitment." (PMID 37189844, 2023). "Furthermore, IL-6 has been found associated with severe asthma in adults and in obese subjects." (PMID 35055456, 2022). "We speculate that the IL-6 rs1800795 polymorphism may be the same as factors such as residence, lifestyle, and eating habits, which is the reason for the different susceptibilities of different ethnic groups to asthma and allergic rhinitis." (PMID 35368692, 2022). "Children carrying the minor allele of rs139089467 had lower IL-6 levels in response to the bacterial stimulus Fla and were more likely to have had an unscheduled visit to a primary care physician for asthma in the first 8 years of life (20.6% vs 15.8%, P = 0.03)." (PMID 35931775, 2022). "Finally, as an exemplar of the strong heritable component of immune responses, we identified several novel cQTL for IL-6 induction by bacterial stimuli and observed that genetic associates of lower IL-6 production were linked to markers of more severe asthma in this population." (PMID 35931775, 2022). "Similarly, IL‐1β and IL‐6 are pro‐inflammatory cytokines released by macrophages and dendritic cells and their upregulation have been associated with allergic reactions such as asthma and urticaria." (PMID 34873877, 2022). "In addition, a significant association was found between serum IL-6 and asthma attack risk." (PMID 34402724, 2021).
asthma (continued). "Taken together, these results suggested that macrophage-derived IL-6 plays a critical pathogenic role in the HDM-induced asthma model and that IL-6 from this cell type may contribute to the induction or amplification of Th2 inflammatory response during acute asthma." (PMID 30534125, 2018). "Higher concentrations of IL-6 have been shown in induced sputum from asthmatic patients compared to controls, in the plasma of asthmatic patients, and a genome-wide association study has previously highlighted the IL-6 receptor gene locus as a possible risk locus for asthma." (PMID 30157189, 2018). "Mechanistically, IL-6-driven STAT3 signaling has been implicated in steroid resistance and persistent airway inflammation in Th17-skewed asthma models, reinforcing the clinical importance of these cytokine patterns." (PMID 41601686, 2026). "Instillation of poly(I:C) to this OVA‐induced, experimental asthma model elicited an immediate and profound IL‐6 response and aggravated the allergic airway inflammation." (PMID 41099307, 2026). "Epidemiological studies suggest that respiratory viral infections are major triggers of asthma exacerbations, and clinical studies have suggested the involvement of an increased interleukin‐6 (IL‐6) release." (PMID 41099307, 2026). "Mechanistic studies have established that non-T2 asthma involves prominent activation of Th1 and Th17 responses, with key roles for IL-6, IL-17A, and TNF-α in driving neutrophilic inflammation and airway hyperresponsiveness." (PMID 41601686, 2026). "Interleukin-6 (IL-6) trans-signaling modulates immune responses in asthma, yet the mechanisms linking this pathway to Th17 skewing in neutrophilic asthma remain incompletely defined." (PMID 41972168, 2026). "An exaggerated IL‐6 release is required for exacerbation of experimental asthma, potentially the result of viral PAMP‐induced immune training of airway epithelial cells." (PMID 41099307, 2026). "TNF acts as a key receptor that promotes the expression and release of inflammatory mediators such as IL-6, contributing to excessive mucus secretion and airway inflammation characteristic of asthma." (PMID 41599256, 2026). "We deployed a multilevel, translational pipeline to identify the role of IL‐6, its gene methylation and downstream signalling in a murine model of experimental asthma exacerbation, in vitro tissue culture models and human cohorts." (PMID 41099307, 2026). "This study aims to investigate how immune activation influences the epigenetic regulation and expression of the Interleukin‐6 (IL‐6) gene during asthma exacerbations." (PMID 41099307, 2026). "This study investigates how immune activation influences the epigenetic regulation and expression of the IL‐6 gene during asthma exacerbations." (PMID 41099307, 2026). "Though the cellular source of IL‐6 in asthma exacerbations remains uncertain, it is known to be produced by innate immune cells (e.g., macrophages, neutrophils, dendritic cells), T cells and structural cells (e.g., epithelial or endothelial cells)." (PMID 41099307, 2026). "Elevated IL-4, IL-9, and TNF-α were observed in non-T2 asthma compared with T2-high asthma, while children exhibited higher levels of IL-2, IL-6, IFN-γ, and IL-17A than adults." (PMID 41601686, 2026). "Asthma patients with a trained IL‐6 response, characterised by IL6 gene hypomethylation, exhibit more frequent exacerbations." (PMID 41099307, 2026). "Poly(I:C)‐induced excessive IL‐6 release, driven by training of innate immunity in the respiratory epithelium, is essential for the exacerbation of experimental asthma." (PMID 41099307, 2026). "In the present study, we found that poly(I:C)‐induced exacerbation of experimental asthma in mice depends on IL‐6 release, and that repeated exposure to poly(I:C) leads to increased IL‐6 release by BECs and increased airway inflammation." (PMID 41099307, 2026).
asthma (continued). "Children with non-T2 asthma exhibited markedly higher levels of IL-6, IFN-γ, and IL-17A than adults, consistent with a Th1/Th17-dominant immune phenotype." (PMID 41601686, 2026). "By examining molecular mechanisms of immune training, we seek to elucidate how IL‐6‐driven inflammatory pathways contribute to airway dysfunction and worsening asthma symptoms." (PMID 41099307, 2026). "We decided to further focus on AECs due to several aspects: (I) Recent studies highlighted the bronchial epithelium as a major contributor to IL‐6 production in asthma patients and in experimental models, suggesting its significance in exacerbations." (PMID 41099307, 2026). "What is the pathophysiological role of IL‐6 in asthma exacerbation, and which mechanisms lead to enhanced IL‐6 release?" (PMID 41099307, 2026). "In conclusion, an exaggerated IL‐6 release is required for exacerbation of experimental asthma, resultant of viral PAMP‐induced innate immune respiratory epithelium training." (PMID 41099307, 2026). "Previous studies have found that IL-6 and 23 secreted by DCs induce Th17 differentiation, which was a major mechanism controlling the recruitment of neutrophils in asthma airways." (PMID 41196933, 2025). "To ascertain factors associated with high IL-6 in asthma, we performed logistic regression of high IL-6 patients with asthma only (n = 305 or 9% of the cohort)." (PMID 39714726, 2025). "Emerging evidence suggests shared mechanisms between asthma and fibromyalgia, including neurogenic inflammation mediated by cytokines (e.g. IL-6, TNF-α) and central sensitization." (PMID 41017472, 2025). "Inhibition of STAT3 has been reported to reduce eosinophilic infiltration, cytokine release, and airway hyperresponsiveness in asthma models, while also attenuating IL-6-mediated inflammatory signaling and airway remodeling in COPD." (PMID 41304567, 2025). "In a small study with two pediatric patients with severe, steroid-resistant asthma, IL-6 blockade with tocilizumab resulted in immunological and clinical improvement of asthma control and exacerbations." (PMID 39714726, 2025). "Asthma is one of the chronic respiratory inflammatory diseases, and in almost asthma patients, the levels of inflammation-related cytokines, such as IL-6 and TNF-α, are elevated." (PMID 40323927, 2025). "IL-6 is also an important inflammatory factor involved in neutrophil-inflammation-mediated osteoporosis in asthma patients." (PMID 39857779, 2025). "Patients with asthma exhibit elevated serum levels of cytokines such as IL6, IL8, TNFα, and IL1β, which activate immune cells including neutrophils, macrophages, and lymphocytes, contributing to the initiation and development of inflammatory responses." (PMID 40598285, 2025). "In the asthma group, there was a statistically significant decrease in the proportion of patients with IL-6 levels above the reference level 12 months after vaccination." (PMID 39937802, 2025). "Topological analysis examined node centrality (degree, betweenness) to identify critical targets, exemplified by a study on andrographolide asthma, where IL-6/MMP9 hubs and Th17 pathways were validated." (PMID 40732361, 2025). "Our study revealed an inverse relationship of the A/L ratio with the number of eosinophils in peripheral blood, as well as with proinflammatory cytokines, such as IL-6, IL-8 and TNFα in patients with asthma." (PMID 40361972, 2025). "This has been linked to increased levels of cytokines, such as IL-18, IL-6, TNF-α, leukotrienes, and chemokines, in patients with asthma." (PMID 40770020, 2025). "Another study demonstrated that continuous intranasal exposure to A. lwoffii elicited a proinflammatory response that conferred protection against asthma in mice through an IL-6-dependent mechanism involving the epigenetic activation of IL-10 production." (PMID 40806756, 2025).
asthma (continued). "We compared lung function between IL-6 levels (high: > 4.979 pg/ml and low: < 4.979 pg/ml) within asthma (presence or absence aka normal) and BMI (lean < 25 kg/m2 or non-lean > 25 kg/m2) groups." (PMID 39714726, 2025). "A recent study found that it had asthma protection operating through IL-6-mediated epigenetic activation of IL-10 production and with associated effects on the intestinal microbiome." (PMID 40401951, 2025). "AKT1, downstream of PI3 K, can regulate various growth factors impacting lung function in asthma, modulate inflammatory cytokine IL6, and inhibit proliferation in human bronchial smooth muscle cells." (PMID 40420184, 2025). "Uric acid induces the upregulation of endothelin-1 expression, and inflammatory mediators, such as endothelin-1, IL-6, and IL-8, have been shown to promote mucus secretion, airway swelling, and bronchial hyperreactivity." (PMID 40299440, 2025). "IL-6 is thought to evoke immune responses typical of both T2 and non-T2 inflammation as evidenced by increased serum eosinophilia and fraction of exhaled nitric oxide, as well as Th17-mediated neutrophilia in patients with high IL-6 and asthma." (PMID 39714726, 2025). "BALF containing Nets from a Sendai virus-induced asthma model directly stimulated DCs to release a substantial amount of IL-6." (PMID 41196933, 2025). "In the context of chronic disorders such as asthma 48 and chronic myelogenous leukemia 49, mediators like G-CSF and IL-6 have been previously identified as disruptors of the hematopoietic hierarchy." (PMID 40521205, 2025). "The impact of weight on the interaction between IL-6 and asthma is also an important consideration as leptin can increase IL-6 levels." (PMID 39714726, 2025). "One of the mechanisms of IL-6 in asthma severity and poor response to bronchodilator is via vascular endothelial growth factor (VEGF)." (PMID 40217808, 2025). "IL-6 functions as both a pro-inflammatory marker and an active contributor to asthma pathogenesis, potentially driving lung function decline in untreated patients." (PMID 40443529, 2025). "Purpose of this study is to investigate dynamics of CRP, serum cytokines (IL-2, IL-6, IL-10, IL-17) in patients with asthma and COPD, as well as to perform a correlation analysis with the clinical manifestations of the diseases within a year after vaccination." (PMID 39937802, 2025). "Resistin is linked to asthma, COPD, fibrosis, and acute lung injury, while adiponectin suppresses pulmonary inflammation by inhibiting TNF-α, IL-6, and chemokine production." (PMID 40453581, 2025). "In asthma patients before the vaccination, the IL-6 level is directly correlated with the level of serum CRP (r = 0.68; p <0.05." (PMID 39937802, 2025). "The relationship between the A/L ratio and proinflammatory cytokines IL-6, IL-8 and TNFα playing a pathogenetic role both in patients with asthma and in patients with abdominal obesity was also studied." (PMID 40361972, 2025). "In particular, IL-6 and TNF-α are deeply associated with asthma severity, such as airway remodeling and fibrosis in the late stage." (PMID 40323927, 2025). "This study utilized the Coronary Artery Risk Development in Young Adults (CARDIA) database, comprised of 5115 adults, to investigate the relationship between IL-6 levels, asthma, race, and metabolic dysfunction." (PMID 39714726, 2025). "Even within the lean patients with asthma, having high IL-6 appeared to result in lower FEV1; however, this difference was not statistically significant (p = 0.3582)." (PMID 39714726, 2025). "In terms of anti-inflammation, E10 dose-dependently inhibits the levels of inflammatory factors NO and IL-6, which deserves further exploration in the treatment of asthma." (PMID 40078565, 2025). "Dynamics of IL-6 level in asthma and COPD patients vaccinated against influenza and healthy individuals (reference value: Less than 10 pg/mL)." (PMID 39937802, 2025).